EPB41L4B (erythrocyte membrane protein band 4.1 like 4B)
Description:
Up-regulates the activity of the Rho guanine nucleotide exchange factor ARHGEF18 (By similarity). Involved in the regulation of the circumferential actomyosin belt in epithelial cells. Promotes cellular adhesion, migration and motility in vitro and may play a role in wound healing. May have a role in mediating cytoskeletal changes associated with steroid-induced cell differentiation.
Synonyms: EHM2; LULU2; CG1
Tractability: Antibody: its Gene Ontology location is reachable by antibodies, with high confidence; the Human Protein Atlas places it where antibodies can reach. PROTAC: ubiquitination databases record sites on it; its protein half-life has been measured.
Gene: Protein-coding gene on chromosome 9 (109,171,463 to 109,321,067, reverse strand). Ensembl gene ENSG00000095203.
Subcellular location: Cytoplasm; Cell junction, tight junction
Subcellular location (Human Protein Atlas): Cytosol; Plasma membrane
Gene Ontology:
Molecular function: structural constituent of cytoskeleton; cytoskeletal protein binding
Biological process: actomyosin structure organization; positive regulation of cell adhesion; positive regulation of gene expression; positive regulation of keratinocyte migration; regulation of keratinocyte proliferation; wound healing
Cellular component: apical part of cell; cytoplasm; cytoskeleton; bicellular tight junction
Genetic constraint (gnomAD): Loss-of-function variants: 16 observed, 85.01 expected, observed/expected ratio (o/e) 0.19, 90% interval 0.13 to 0.29. The upper end of that interval is the gene's LOEUF score, 0.29, which puts it in group 1 of 6, group 1 being the genes least tolerant of losing a copy. Missense variants: 825 observed, 915.98 expected, observed/expected ratio (o/e) 0.9, 90% interval 0.85 to 0.95. Synonymous variants: 326 observed, 353.52 expected, observed/expected ratio (o/e) 0.92, 90% interval 0.84 to 1.01.
Homologues: Orthologues: chimpanzee EPB41L4B (99% identical), pig EPB41L4B (93% identical), dog EPB41L4B (93% identical), rat Epb41l4b (91% identical), mouse Epb41l4b (90% identical), macaque EPB41L4B (89% identical), guinea pig EPB41L4B (88% identical), rabbit EPB41L4B (83% identical), tropical clawed frog epb41l4b (41% identical), Drosophila melanogaster yrt (36% identical), zebrafish epb41l4b (31% identical), Caenorhabditis elegans frm-2 (26% identical), and 5 more. Paralogues in human: EPB41L5 (39% identical), EPB41L2 (23% identical), EPB41L3 (23% identical), EPB41 (22% identical), EPB41L4A (22% identical), EPB41L1 (22% identical), FRMD3 (17% identical), FRMD5 (16% identical), FRMD6 (13% identical), MYLIP (13% identical).
Diseases named in the same sentence as EPB41L4B in open-access papers:
EPB41L4B is named in the same sentence as 19 diseases in open-access papers, as found by Europe PMC text mining. Sharing a sentence is not in itself a finding about the gene and the disease. The quoted sentences say what the papers report.
breast carcinoma (4 papers, 2015 to 2021). "The risk score of breast cancer prognosis was determined with the following formula: RiskScore = 0.629*ANO6 + 0.147*CELSR3 + 0.381*CLDN7+ 0.273*EPB41L4B-0.357*FAM166B -0.843*GPLD1–0.202*LEF1–0.202*PPARG -0.127*SUSD3." (PMID 34364397, 2021). "Loss of EPB41L4B led to in inhibition of in vitro proliferation of breast cancer cell lines, and increased EPB41L4B levels were correlated with disease progression and poor prognosis." (PMID 30440051, 2018). "MKLN1 has been previously associated with childhood asthma, SORBS1 with suicide risk and childhood obesity in Hispanics, SLC1A2 with fatty acid levels, essential tremor, and other traits, EPB41L4B with wound healing, PTPN3 with cancer, and FGF3 with breast cancer and deafness." (PMID 26569114, 2015).
prostate carcinoma (4 papers, 2007 to 2018). A carcinoma that arises from epithelial cells of the prostate gland. "Intriguingly, increased expressions of ABCB6, BTG1 and EPB41L4B were found in glioma, thyroid carcinoma and prostate cancer, respectively, but the underlying mechanism stays unclear." (PMID 25575809, 2015). "EPB41L4B was first reported as a gene highly expressed in metastatic melanoma cell lines and is reported to be overexpressed in prostate cancer." (PMID 30440051, 2018). "We have previously reported downregulation of EPB41L3 encoding protein band 4.1B and upregulation of EPB41L4B encoding EHM2, respectively, in prostate cancer, in accord with observations by other groups." (PMID 20860828, 2010). "Previous studies have concurrently reported changes in the expression of EPB41L3/4.1B and EPB41L4B/EHM2 in many prostate cancers." (PMID 20860828, 2010). "Real-time RT-PCR revealed GADD45A, MX1, EPB41L3/DAL1, and FBLN1 as generally downregulated in prostate cancer, whereas HOXB13 and EPB41L4B were upregulated." (PMID 17280610, 2007).
metastatic melanoma (2 papers, 2007 to 2018). A melanoma that has spread from its primary site to another anatomic site. "EHM2 encoded by EPB41L4B was identified as overexpressed in metastatic melanoma cells." (PMID 17280610, 2007).
cyst (1 paper, 2021). A sac-like closed membranous structure that may be empty or contain fluid or amorphous material. "However, IPMN lesions showed heterogeneous pattern of EPB41L4B staining, with some parts of the cyst layer showing positive staining and some parts negative." (PMID 34069007, 2021).
cancer (6 papers, 2007 to 2021). A tumor composed of atypical neoplastic, often pleomorphic cells that invade other tissues. "In contrast, a more distant paralog, EPB41L4B encoding EHM2, was strongly upregulated in the 'both' group, and in cancers overall." (PMID 17280610, 2007). "EPB41L3 mRNA was highly significantly (Mann-Whitney p < 0.001) diminished and EPB41L4B increased (p = 0.002) in these cancer tissues." (PMID 20860828, 2010). "EPB41L1 and EPB41L3 were significantly downregulated and EPB41L4B was upregulated in cancer tissues." (PMID 20860828, 2010). "It is evident from the figure that the majority of ERG-high cancers displayed decreased expression of EPB41L3 and increased expression of EPB41L4B, whereas most of the ERG-low carcinomas had expression levels of the two genes within the range of benign tissues." (PMID 20860828, 2010).
tumor (4 papers, 2006 to 2021). "To address the general significance of this finding, we examined whether the relationship between CRB3 and EPB41L4B expression is observed more broadly in immortalized breast epithelial cell lines and in tumor cell lines derived from patient samples." (PMID 30440051, 2018). "Repression of NTN4 and HYAL1 may promote cell migration and invasive growth, whereas BAI3, VWF, and EPB41L4B probably participate in angiogenesis, attachment of tumor cells to endothelial surfaces, or reflect vascular structures in the tumors." (PMID 17054779, 2006).
EPB41L4B also shares sentences with these, for which no sentence is quoted: cervical carcinoma (2 papers); prostate adenocarcinoma (2); childhood asthma (1); colon cancer (1); deafness (1); essential tremor (1); glioma (1); lung carcinoma (1); melanoma (1); metastatic cancer (1); thyroid carcinoma (1); type 2 diabetes (1); Wilms tumor (1).